WFDC9 (WAP four-disulfide core domain 9)
Synonyms: WAP9; dJ688G8.2
Tractability: Antibody: UniProt places it where antibodies can reach, with high confidence; UniProt predicts a signal peptide or a membrane-spanning region; its Gene Ontology location is reachable by antibodies, with medium confidence.
Gene: Protein-coding gene on chromosome 20 (45,607,939 to 45,631,284, reverse strand). Ensembl gene ENSG00000180205.
Subcellular location: Secreted
Gene Ontology:
Molecular function: protein binding; serine-type endopeptidase inhibitor activity
Biological process: antibacterial humoral response; innate immune response
Cellular component: extracellular region
Genetic constraint (gnomAD): Loss-of-function variants: 9 observed, 9.63 expected, observed/expected ratio (o/e) 0.93, 90% interval 0.56 to 1.6. That is too few expected variants to judge how well the gene tolerates losing a copy. Missense variants: 83 observed, 107.3 expected, observed/expected ratio (o/e) 0.77, 90% interval 0.65 to 0.93. Synonymous variants: 33 observed, 33.5 expected, observed/expected ratio (o/e) 0.99, 90% interval 0.75 to 1.32.
Homologues: Orthologues: chimpanzee WFDC9 (97% identical), macaque WFDC9 (87% identical), rabbit WFDC9 (57% identical), guinea pig WFDC9 (54% identical), rat Wfdc9 (54% identical), dog WFDC9 (52% identical), mouse Wfdc9 (52% identical), Drosophila melanogaster CG5639 (21% identical), Caenorhabditis elegans C08G9.2 (13% identical). Paralogues in human: WFDC11 (38% identical), WFDC10A (30% identical), WFDC10B (28% identical), WFDC13 (24% identical), WFDC3 (20% identical), WFDC5 (20% identical), PI3 (19% identical), SLPI (18% identical), WFDC12 (15% identical).